IPO13 (importin 13)
Description:
Functions in nuclear protein import as nuclear transport receptor. Serves as receptor for nuclear localization signals (NLS) in cargo substrates. Is thought to mediate docking of the importin/substrate complex to the nuclear pore complex (NPC) through binding to nucleoporin and the complex is subsequently translocated through the pore by an energy requiring, Ran-dependent mechanism. At the nucleoplasmic side of the NPC, Ran binds to the importin, the importin/substrate complex dissociates and importin is re-exported from the nucleus to the cytoplasm where GTP hydrolysis releases Ran. The directionality of nuclear import is thought to be conferred by an asymmetric distribution of the GTP- and GDP-bound forms of Ran between the cytoplasm and nucleus (By similarity). Mediates the nuclear import of UBC9, the RBM8A/MAGOH complex, PAX6 and probably other members of the paired homeobox family. Also mediates nuclear export of eIF-1A, and the cytoplasmic release of eIF-1A is triggered by the loading of import substrates onto IPO13.
Synonyms: Imp13; Kap13; RanBP13; KIAA0724; LGL2
Tractability: Small molecule: a structure with a bound ligand is known; it has a binding pocket of medium quality. PROTAC: ubiquitination databases record sites on it; its protein half-life has been measured.
Gene: Protein-coding gene on chromosome 1 (43,946,830 to 43,968,024, forward strand). Ensembl gene ENSG00000117408.
Subcellular location: Cytoplasm; Nucleus
Gene Ontology:
Molecular function: protein binding; small GTPase binding
Biological process: protein import into nucleus; intracellular protein transport
Cellular component: cytoplasm; nucleus
Genetic constraint (gnomAD): Loss-of-function variants: 27 observed, 114.82 expected, observed/expected ratio (o/e) 0.24, 90% interval 0.17 to 0.32. The upper end of that interval is the gene's LOEUF score, 0.32, which puts it in group 1 of 6, group 1 being the genes least tolerant of losing a copy. Missense variants: 766 observed, 1,215.2 expected, observed/expected ratio (o/e) 0.63, 90% interval 0.59 to 0.67. Synonymous variants: 409 observed, 487.67 expected, observed/expected ratio (o/e) 0.84, 90% interval 0.77 to 0.91.
Homologues: Orthologues: chimpanzee IPO13 (100% identical), rabbit IPO13 (99% identical), dog IPO13 (99% identical), mouse Ipo13 (99% identical), guinea pig IPO13 (98% identical), macaque IPO13 (98% identical), rat Ipo13 (96% identical), zebrafish ipo13b (81% identical), tropical clawed frog ipo13 (81% identical), Drosophila melanogaster cdm (29% identical), Caenorhabditis elegans T16G12.6 (18% identical). Paralogues in human: TNPO3 (23% identical).
Diseases named in the same sentence as IPO13 in open-access papers:
IPO13 is named in the same sentence as 17 diseases in open-access papers, as found by Europe PMC text mining. Sharing a sentence is not in itself a finding about the gene and the disease. The quoted sentences say what the papers report.
asthma (2 papers, 2009 to 2016). "Family-based haplotype association analysis of IPO13 polymorphisms on methacholine hyperresponsiveness (PC20) in childhood asthma." (PMID 19619331, 2009). "Family-based association analysis of IPO13 polymorphisms on methacholine hyperresponsiveness (PC20) in childhood asthma." (PMID 19619331, 2009). "Herein, we observed significant associations of common IPO13 polymorphisms with airway responsiveness (the most dynamic treatment response phenotype in the CAMP clinical trial) among children with mild-to-moderate asthma." (PMID 19619331, 2009). "As outlined in the introduction, we initially hypothesized that IPO13 polymorphisms would impact individual responsiveness to inhaled corticosteroid responsiveness for the treatment of asthma given the documented role of IPO13 as an active nuclear transporter for receptor-bound glucocorticoid." (PMID 19619331, 2009). "Given its demonstrated ability to mediate anti-inflammatory GC effects (particularly in airway epithelium), we considered that IPO13 represented a compelling biologic candidate gene for pharmacogenetic responsiveness to glucocorticoid therapy for asthma." (PMID 19619331, 2009). "Polymorphisms of IPO13 have been associated with airway hyper-responsiveness and reactivity in children with asthma, suggesting that IPO13 variation might improve endogenous glucocorticoid bioavailability in the cell nucleus." (PMID 27688786, 2016). "We have demonstrated that genetic variation in IPO13 is associated with reduced airway hyperresponsiveness among children with mild-to-moderate asthma who are not using long-term inhaled corticosteroids." (PMID 19619331, 2009). "We hypothesize that common IPO13 genetic variation influences the anti-inflammatory effects of inhaled corticosteroids for the treatment of asthma, as measured by change in methacholine airway hyperresponsiveness (AHR-PC20)." (PMID 19619331, 2009).
schizophrenia (2 papers, 2020 to 2023). A major psychotic disorder characterized by abnormalities in the perception or expression of reality. "Both IPO13 and RIN3 showed a general high reactivity among all samples, while PAGE2B reactivity was observed in two schizophrenia subjects and two controls." (PMID 33208725, 2020). "As expected, there was also limited concordance between schizophrenia and ADHD (r = 0.0705), particularly for downregulated genes, and six (MAD1L1, KDM4A, IPO13, ATP6V0B, DPH2, PTPRF) of the nine placental genes associated with ADHD were also significantly associated with schizophrenia." (PMID 37188697, 2023).
airway hyperresponsiveness (1 paper, 2009). "A second possible mechanism of action is that IPO13 variants improve airway hyperresponsiveness by enhancing the local anti-inflammatory effects of circulating, endogenous GCs by facilitating increased GR transport into the nucleus and thus increasing the effective bioavailability of endogenous GC." (PMID 19619331, 2009). "It is conceivable that IPO13 variation impacts airway hyperresponsiveness by altering airway anatomy through changes during airway morphogenesis and development." (PMID 19619331, 2009).
endometriosis (1 paper, 2014). The growth of functional endometrial tissue in anatomic sites outside the uterine body. "The list of stemness-related genes enhanced in endometriosis is continuously expanding with the identification of novel markers, such as importin 13 (IPO13)." (PMID 25593975, 2014).
large-cell lung carcinoma (1 paper, 2020). "Additionally, the IPO13 mRNA levels in 156 patient samples showed that the IPO13 expression was higher in large-cell lung carcinoma, squamous cell lung carcinoma, and lung adenocarcinoma than in normal tissues." (PMID 33082305, 2020).
lung adenocarcinoma (1 paper, 2020). A carcinoma that arises from the lung and is characterized by the presence of malignant glandular epithelial cells. "Furthermore, based on the Oncomine database, we found statically significant overexpression of IPO13 in lung adenocarcinoma compared with normal lung." (PMID 33082305, 2020).
lung carcinoma (1 paper, 2020). "IHC analysis confirmed the positive correlation between the expression levels of IPO13 and hTERT in the tumor tissues from patients with lung cancer." (PMID 33082305, 2020). "Correspondingly, in vivo experiments again demonstrated that IPO13 promotes the progression of lung cancer by mediating RFPL3’s nuclear translocation and upregulation of hTERT expression." (PMID 33082305, 2020). "IPO13 interacted with RFPL3 in lung cancer cells, and the knockdown of IPO13 led to the cytoplasmic accumulation of RFPL3, the decreased anchoring of RFPL3 at hTERT promoter, and the downregulation of hTERT expression." (PMID 33082305, 2020). "A nuclear transporter protein IPO13 was highly expressed in the lung epithelial cells, and is rarely studied in lung cancer." (PMID 33082305, 2020). "IPO13 is highly expressed in lung cancer tissue (high IPO13 in 20 cases, and low IPO13 in 10 cases) in comparison with adjacent normal tissues." (PMID 33082305, 2020). "Regarding the finding that RFPL3 localized in the nucleus in lung cancer cells, we speculate that IPO13 might participate in the nucleocytoplasmic transport of RFPL3." (PMID 33082305, 2020). "In our current study, we provide the first evidence that IPO13, as a nucleocytoplasmic shuttling protein, is involved in RFPL3 translocation from the cytoplasm to the nucleus in lung cancer cells." (PMID 33082305, 2020). "To clarify the role of hTERT in IPO13-mediated NSCLC cell growth, which is transcriptionally regulated by RFPL3 in lung cancer, we first measured hTERT expression at protein and mRNA levels in A549 and H1299 cells." (PMID 33082305, 2020). "In summary, our paper exposes a novel pathway by which IPO13 facilitates the nuclear entry of RFPL3, which acts as a specific transcription factor of hTERT to control its expression and to be further involved in lung cancer development." (PMID 33082305, 2020). "However, the relationship between the molecular expression level of IPO13 and its potential function in lung cancer development has not been defined clearly." (PMID 33082305, 2020).
non-small cell lung carcinoma (1 paper, 2020). A group of at least three distinct histological types of lung cancer, including non-small cell squamous cell carcinoma, adenocarcinoma, and large cell carcinoma. "IPO13 protein levels were evaluated in three non-small-cell lung cancer cell lines compared with immortalized bronchial epithelial cells (HBE)." (PMID 33082305, 2020).
osteoporosis (1 paper, 2019). A condition of reduced bone mass, with decreased cortical thickness and a decrease in the number and size of the trabeculae of cancellous bone (but normal chemical composition), resulting in increased fracture incidence. "IPO13 is thus possibly associated with glucocorticoid signaling, although its role in glucocorticoid-induced osteoporosis is unknown." (PMID 31882850, 2019).
pterygium (1 paper, 2013). A wedge-shaped fibrovascular lesion arising from the bulbar conjunctiva and extending to the cornea. "Collectively, these findings indicate that IPO13 plays a role in the pathogenesis of pterygia and the underlying mechanism of IPO13 in the pterygium is via regulating the expression of K17 and nuclear entry of c-Jun." (PMID 23559854, 2013). "IPO13 activity was significantly increased in the epithelium of the pterygium, compared to the normal conjunctiva, suggesting an association of IPO13 with the pterygium." (PMID 23559854, 2013). "Here we investigated the role of IPO13 in the pathogenesis of pterygium and the underlying mechanism including interaction with other cell proliferation–related factors: keratin 17 (K17), a lesional protein and a member of the type I keratins, and c-Jun, a protein of the activator protein-1 complex." (PMID 23559854, 2013). "In the present study, we demonstrated that IPO13 may play a role in the pathogenesis of pterygium, and the underlying mechanism may be through modulation of K17 and c-Jun." (PMID 23559854, 2013). "In the present study, we for the first time investigated the role of IPO13 in the pathogenesis of pterygium and the underlying mechanism including interaction with other cell proliferation–related factors, such as K17, a type I keratin, and c-Jun, a protein of the activator protein-1 (AP-1) complex." (PMID 23559854, 2013). "To further study the mechanism of IPO13 in the pathogenesis of the pterygium, we also investigated the interaction of IPO13 with the transcription factor c-Jun, a prototypic member of AP-1." (PMID 23559854, 2013). "In the present study, we continuously investigated the role of IPO13, by focusing on the epithelium of the pterygium and the interaction of IPO13 with other cell proliferation–related factors, K17 and c-Jun." (PMID 23559854, 2013). "In contrast to the normal conjunctiva, IPO13 activity was significantly increased in the epithelium of the pterygium." (PMID 23559854, 2013). "As cell hyperproliferation partially contributes to the pathogenesis of the pterygium, we examined and focused on the effects of IPO13 on cell proliferation of the pterygium using cultured PECs." (PMID 23559854, 2013). "IPO13 was colocalized with K17 in the epithelium of the pterygium, and overexpression or knockdown of the IPO13 gene induced upregulation or downregulation of K17 expression in PECs, respectively." (PMID 23559854, 2013). "To confirm the increased levels of IPO13 in the pterygium, we performed western blotting with the anti-IPO13 antibody." (PMID 23559854, 2013). "IPO13 was highly expressed in the pterygium specimens, stained dominantly in the basal layer of epithelium, compared to the normal conjunctiva (n=10 in each group)." (PMID 23559854, 2013). "IPO13 levels were statistically significantly increased in the primary and recurrent pterygium, compared with normal conjunctiva (n=3 in each group)." (PMID 23559854, 2013). "IPO13 activity was significantly increased in the basal layer of the epithelium of the pterygium." (PMID 23559854, 2013). "To further understand the role of IPO13 in the pathogenesis of the pterygium, we next investigated the interaction of IPO13 with the cell proliferation–related factor, K17, which, as a lesional protein, is correlated with robust inflammation and epithelium proliferation." (PMID 23559854, 2013). "Further, IPO13 expression was highest in the recurrent pterygium." (PMID 23559854, 2013). "The evidence presented provides a hint that suppressing IPO13 may have a potential therapeutic effect on the development of the pterygium." (PMID 23559854, 2013). "Our evidence suggested that IPO13 might play a role in the cell proliferation of the pterygium via regulating K17 expression." (PMID 23559854, 2013). "We provided novel evidence that IPO13 may contribute to the pathogenesis of pterygium via modulation of K17 and c-Jun." (PMID 23559854, 2013).
pterygium (continued). "In the present study, we for the first time investigated the role of IPO13, a member of the importin-β family of nuclear import proteins, in the pathogenesis of the pterygium and the interaction of IPO13 and other cell proliferation–related factors, K17 and c-Jun." (PMID 23559854, 2013). "We demonstrated that IPO13 was colocalized with K17 in the epithelium of pterygium." (PMID 23559854, 2013). "However, IPO13 was colocalized with K17 in the epithelium of the pterygium." (PMID 23559854, 2013). "The role of IPO13 in ocular epithelial diseases such as pterygium has not been previously reported." (PMID 23559854, 2013).
cancer (2 papers, 2020 to 2022). A tumor composed of atypical neoplastic, often pleomorphic cells that invade other tissues. "However, the expression level and the potential function of IPO13 in various cancers are still unknown." (PMID 33082305, 2020). "Besides, IPO13 was found to play a critical role in NSCLC progression, which was implied by the proliferation promotion of NSCLC cells in vitro and the influence on tumor growth of an NSCLC cancer model in vivo." (PMID 33082305, 2020).
tumor (2 papers, 2020 to 2025). "Notably, deficiency of RNF31 and IPO13 greatly impaired tumour progression upon PTX administration, as indicated by significantly reduced increases in the size and weight of the xenograft tumours." (PMID 39915011, 2025). "The tumours in the IPO13 knockdown plus paclitaxel group were slightly smaller than those in the RNF31 knockdown plus paclitaxel group, while the difference was not statistically significant (p = .676)." (PMID 39915011, 2025). "According to the positive correlation between IPO13 upregulation and EGFR mutations in NSCLC tumor, GSEA was performed on the gene ontology (GO) and KEGG databases." (PMID 33082305, 2020). "Moreover, IPO13 silencing suppressed tumor growth in vitro and in vivo." (PMID 33082305, 2020). "The remaining tumours also showed strongly reduced nuclear ALYREF levels in tumour tissues of the RNF31 knockdown and IPO13 knockdown groups, as detected by western blotting and IHC assays." (PMID 39915011, 2025). "Consistently, the mRNA and protein levels of TUBB3, STMN1, and TAU were dramatically reduced in the tumour tissues of the RNF31 knockdown and IPO13 knockdown groups treated with PTX." (PMID 39915011, 2025).
diseases of the central nervous system (1 paper, 2025). "These include genes involved in neurodegeneration (EIF5), diseases of the central nervous system (IPO13, ST3GAL3), tobacco addiction (CHRNB4, PSMA4), fatty acid metabolism (ACSBG1), and skin conditions (HYI, ELOVL1)." (PMID 40074595, 2025).
IPO13 also shares sentences with these, for which no sentence is quoted: idiopathic inflammatory myopathies (1 paper); Lissencephaly (1); melanoma (1); squamous cell lung carcinoma (1).